CSF1R (colony stimulating factor 1 receptor)
Diseases named in the same sentence as CSF1R in open-access papers (continued):
Sharing a sentence is not in itself a finding about the gene and the disease.
asthma (4 papers, 2021 to 2024). "CSF1R expression was increased in HDM‐induced experimental asthma, and its gene polymorphism was associated with increased asthma risk, in which, CSF1R + 22693T>C may be predisposed to asthma." (PMID 37249291, 2023). "It has been reported that airway epithelial cell‐derived CSF1 and CSF1R be involved in the pathogenesis of asthma, especially in the activation of dendritic cells (DCs) and subsequent allergic inflammation." (PMID 37249291, 2023). "When exploring the biological impact of other genes mapped to the dmCpGs uniquely associated with father’s pubertal smoking, several were related to genes associated with innate immunity, allergic diseases and asthma development, such as TLR9, CSF1R, DNAJ14, NTRK2 and TPCN1." (PMID 37649101, 2023). "Besides, we also detect the mRNA expression of its receptor (CSF1R), our results showed CSF1R was increased in asthma (p = .0144), A positive correlation between CSF1 and CSF1R was observed (rs = 0.4759, p = .0003)." (PMID 37249291, 2023). "The findings indicated that CSF1 may exert its modulatory role by activating CSF1R in the airway pathogenesis of asthma." (PMID 37249291, 2023). "Additionally, a study has shown that polymorphisms in the CSF-1R gene may be a marker of susceptibility to asthma, with a high expression of the CSF-1R in CD14+ monocytes and neutrophils in subjects with asthma compared to normal controls." (PMID 39457693, 2024). "KEGG pathway analysis results and GSVA results show that genes related to allograft rejection, asthma, and autoimmune thyroid disease pathways were enriched or upregulated in the LAPTM5, C1QC, SLCO2B1 and CSF1R high expression groups." (PMID 33428598, 2021). "CSF1R, the receptor for CSF1, was reportedly involved in the pathogenesis of asthma." (PMID 37249291, 2023).
brain infarction (4 papers, 2017 to 2024). Tissue necrosis in any area of the brain, including the cerebral hemispheres, the cerebellum, and the brain stem. "Notably, the benefit of etifoxine against brain infarction was ablated in mice depleted of microglia using a colony-stimulating factor 1 receptor inhibitor." (PMID 28754131, 2017).
brain injuries (4 papers, 2020 to 2023). "Moreover, the expressions of CSF1 and CSF1R in neurons profoundly increased after a variety of brain injuries." (PMID 33101590, 2020). "Some agents such as CSF1R inhibitors, Liposomal clodronate, and Mac-1-saporin were found to be potent in inducing microglia depletion and its subsequent repopulation, thereby attenuating inflammation after ischemic brain injuries." (PMID 32754016, 2020).
cholangiocarcinoma (4 papers, 2022 to 2023). A carcinoma that arises from the intrahepatic biliary tree (intrahepatic cholangiocarcinoma) or from the junction, or adjacent to the junction, of the right and left hepatic ducts (hilar cholangiocarcinoma). "Another kinase inhibitor, Derazantinib, also found to have activity against CSF1R and is under investigation for cholangiocarcinoma." (PMID 35311155, 2022). "Blocking TAMs with anti-colony stimulating factor 1 receptor (CSF1R) failed to decrease tumour progression in cholangiocarcinoma." (PMID 36154923, 2022). "However, in the murine cholangiocarcinoma (CAA) model, TAM blockade by anti-CSF1R failed to reduce CCA growth due to the compensatory infiltration of G-MDSCs." (PMID 36189283, 2022).
dysosteosclerosis (4 papers, 2021 to 2023). Dysosteosclerosis is a skeletal dysplasia characterized by progressive osteosclerosis and platyspondyly. "The skeletal phenotype of the outbred adult Csf1rko rat closely resembles that of human CSF1R-deficient patients, referred to as dysosteosclerosis." (PMID 34081701, 2021). "Furthermore, few case reports have been published with patients carrying two mutant CSF1R alleles presenting with brain abnormalities, neurodegeneration, and dysosteosclerosis (BANDDOS), and a new entity has been recognized (MIM#618,476)." (PMID 37349768, 2023). "CSF1R mutations cause autosomal-dominant CSF1R-related leukoencephalopathy with axonal spheroids and pigmented glia (CSF1R-ALSP) and autosomal-recessive brain abnormalities, neurodegeneration, and dysosteosclerosis (BANDDOS)." (PMID 37349768, 2023).
fibrosarcoma (4 papers, 2018 to 2025). A malignant mesenchymal fibroblastic neoplasm affecting the soft tissue and bone. "In a recent study performed in colorectal adenocarcinoma and fibrosarcoma mouse models, the depletion of TAMs was obtained by the use of a high-affinity humanized anti-colony-stimulating factor 1 receptor (CSF1R) monoclonal antibody (RG7155)." (PMID 29973487, 2018). "Being a multikinase inhibitor, sorafenib inhibits cell proliferation as well as angiogenesis by inhibiting rapidly accelerated fibrosarcoma (RAF), vascular endothelial growth factor (VEGF), and platelet-derived growth factor (PDGF) pathways in addition to CSF1R." (PMID 37711590, 2023).
Hepatic fibrosis (4 papers, 2020 to 2025). The presence of excessive fibrous connective tissue in the liver. "Moreover, we found that the expression of CSF1R gene, a marker for pan-macrophages reported to be involved in hepatic fibrosis, was also considered as a potential marker for hepatocarcinogenesis." (PMID 37008925, 2023). "The levels of Wisteria floribunda agglutinin+-colony-stimulating factor 1 receptor (WFA+-CSF1R) could reflect the progression of liver fibrosis and possibly evaluate the severity of LC." (PMID 32280697, 2020).
liver cancer (4 papers, 2021 to 2025). An epithelial or non-epithelial malignant neoplasm that arises from the liver. "The expression of CSF-1R with the enrichment of TAMs is correlated with a poor prognosis in various types of cancer, including breast, gastric, pancreas, colon, and liver cancer." (PMID 35455743, 2022). "In rat primary liver cancer models induced by diethylnitrosamine (DEN), a distinct population of AIF1+CSF1R+ MSCs was identified during the chronic inflammation stage." (PMID 40676710, 2025). "In a liver cancer model induced by DEN exposure, AIF1+CSF1R+ MSCs exhibiting elevated expression of sirtuin 1 (SIRT1) was identified within liver tissues undergoing chronic inflammation prior to the onset of cancer." (PMID 40676710, 2025).
liver diseases (4 papers, 2019 to 2021). "Steroids (e.g., dexamethasone), IL-4, IL-10, secretory leukocyte protease inhibitor (SLPI), prostaglandin E2 (PGE2) and colony-stimulating factor 1 receptor (CSF-1R) agonists have been explored for macrophage reprogramming in liver diseases." (PMID 34685739, 2021).
metastatic melanoma (4 papers, 2015 to 2021). A melanoma that has spread from its primary site to another anatomic site. "Based on our results in the SM1 model, we provide preclinical support for the therapeutic combination of BRAF and CSF-1R inhibition currently being tested in patients with BRAFV600 mutant metastatic melanoma (trial NCT01826448)." (PMID 25939769, 2015). "Our data support the combination of CSF-1R inhibition with PLX4032 and provide a strong rationale to translate combined targeted therapy and inhibition of myeloid cells for patients with BRAFV600 mutant metastatic melanoma." (PMID 25939769, 2015).
myocardial infarction (4 papers, 2015 to 2025). Gross necrosis of the myocardium, as a result of interruption of the blood supply to the area, as in coronary thrombosis. "In acute myocardial infarction mouse models, five genes (Ptpn6, Csf1r, Col6a1, Cyba, and Map3k14) have been implicated in the acute myocardial infarction pathway by regulating DNA methylation, suggesting their potential as early methylated biomarkers for clinical diagnosis." (PMID 40428388, 2025). "Most Mac2 immunoreactive cells in healing myocardial infarcts were also identified as CSF1R+ macrophages." (PMID 35296717, 2022). "Taken together, these data indicate that CSF-1R signalling is critical for maintaining cardiac tissue resident M2-polarized macrophage population, which is required for the resolution of inflammation post myocardial infarction and, in turn, for preservation of ventricular function." (PMID 26407006, 2015). "In order to examine the time course of macrophage infiltration in the infarcted myocardium during the various stages of cardiac injury and repair, we used CSF1R-EGFP and CX3CR1GFP reporter mice in a model of non-reperfused myocardial infarction." (PMID 35296717, 2022).
neuroendocrine tumors (4 papers, 2023 to 2025). "Surufatinib, an oral inhibitor of VEGFR1-3, FGFR1 and CSF1R, has shown durable activity in neuroendocrine tumors." (PMID 41275311, 2025). "Surufatinib, approved in China in late 2020 for the treatment of well-differentiated extrapancreatic neuroendocrine tumors (NETs), selectively inhibits VEGFR 1, 2, and 3, FGFR1, and CSF-1R, offering a targeted approach to managing these tumors." (PMID 40149728, 2025). "Sulfatinib is a multi-target kinase inhibitor for treating neuroendocrine tumors, selectively targeting FGFR1/CSF-1R." (PMID 38172256, 2024). "Sulfatinib is a multi-target angio-immuno kinase inhibitor for treating neuroendocrine tumors, selectively targeting FGFR1 and CSF-1R." (PMID 38172256, 2024).
retinal degeneration (4 papers, 2017 to 2023). Degeneration of the retina. "As retinal microglia are dependent on CSF1R signaling for survival and proliferation, we tested here, whether microglia depletion could also be beneficial in a model of light-induced retinal degeneration." (PMID 38288111, 2023). "In this study, we used the colony stimulating factor 1 receptor (CSF1R)-antagonist PLX3397 to investigate the effects of microglia depletion and repopulation in a mouse model of acute retinal degeneration that mimics some aspects of dry AMD." (PMID 38288111, 2023). "To confirm the contribution of microglia to the clearance of synaptic material during retina degeneration in RCS rats, we eliminated microglia with the CSF1R inhibitor PLX3397 (600 ppm), which was fed to 15-day-old RCS rats for 25 days." (PMID 31105708, 2019).
schizophrenia (4 papers, 2021 to 2023). A major psychotic disorder characterized by abnormalities in the perception or expression of reality. "These are to our knowledge the first evidence revealing the involvement of CSF1R in schizophrenia and vascular association of microglia/macrophages in the context of stress." (PMID 37542262, 2023). "Our findings suggest that CSF1R may provide a stress-coping mechanism via regulating microglial/macrophagic association with cerebral vasculature, which might be disturbed in schizophrenia." (PMID 37542262, 2023). "In the present study, we hypothesized that CSF1R-involved microglial/macrophagic functions were associated with schizophrenia-related stress modulation via regulating the brain cortical and subcortical structures." (PMID 37542262, 2023). "However, the exact role of CSF1R in schizophrenia in association with psychosocial stress has remained unclear." (PMID 37542262, 2023). "Microglial/macrophagic CSF1R regulated schizophrenia-associated stress and brain angiogenesis." (PMID 37542262, 2023). "With this approach, it will be possible to manipulate disease-associated microglial genes in iPSC-MG, such as mutated C-X3-C motif chemokine receptor 1 (CX3CR1) in schizophrenia and autism spectrum disorder and mutated CSF1R in hereditary diffuse leukoencephalopathy with spheroid (HDLS)." (PMID 35910250, 2022). "By contrast, our current observation on the blood CSF1R level had minimal drug effect, giving hint on impairment of the CSF1R function in early stage of schizophrenia." (PMID 37542262, 2023). "Lower level of CSF1R mRNA was reported in the cortices and spleens of chronic schizophrenia patients." (PMID 37542262, 2023). "Interestingly, CSF1R has been observed to play potential role in disrupted lipid metabolism in Csf1r knockout livers and the corpora callosa of patients with schizophrenia." (PMID 34867307, 2021). "To better understand the role of microglia or myeloid cells in schizophrenia-related stress regulation, we first studied a cohort of FES patients showing higher stress perception compared to healthy controls (HCs) by measuring their blood transcriptomics, plasma CSF1R levels, and brain structures." (PMID 37542262, 2023). "Decreased expression of the colony-stimulating factor 1 receptor (CSF1R) was found in the spleen but not in the cerebellum and parietal cortex in schizophrenia compared with controls." (PMID 35546942, 2022).
thymoma (4 papers, 2013 to 2024). A neoplasm arising from the epithelial cells of the thymus. "Types A, AB, and B2 thymomas share many of these genes, with additional occurrences of PAX7 and CSF1R in Type A thymoma and ZMYM3 in Type AB thymoma." (PMID 38338833, 2024). "Additionally, the authors documented AKT3, ALK, CSF1R, FGFR4, KRAS, NRAS, and PIK3CA as common mutated genes in thymomas." (PMID 38338833, 2024). "Significant enrichment of mutated genes of the RAS and PI3K-Akt signalling pathways was reported in thymomas (AKT3, ALK, CSF1R, FGFR4, KRAS, NRAS, HRAS, PIK3CA), and their role in thymoma development was suggested." (PMID 35884448, 2022).
acute lymphoblastic leukemia (3 papers, 2023 to 2025). Leukemia with an acute onset, characterized by the presence of lymphoblasts in the bone marrow and the peripheral blood. "CSF-1R inhibition was able to block TAM polarization in mouse models of T-acute lymphoblastic leukemia (ALL) and the association between a CSF-1R inhibitor and vincristine could increase survival of leukemic mice, if compared to vincristine as monotherapy." (PMID 37504315, 2023). "High-resolution breakpoint mapping by Optical Genome Mapping enables precise detection of clinically actionable gene rearrangements in acute lymphoblastic leukemia (ALL), including MEF2D::CSF1R and PAX5::JAK2 fusions—hallmarks of the Philadelphia-like (Ph-like) ALL subtype." (PMID 41228238, 2025).
autoimmune disease (3 papers, 2016 to 2023). A disorder resulting from loss of function or tissue destruction of an organ or multiple organs, arising from humoral or cellular immune responses of the individual to their own tissue constituents. "In fact, the therapeutic potential of the CSF1R kinase inhibitor has been explored in many pathologies such as cancer, bone disease, inflammatory diseases, and other autoimmune disorders, and so several CSF1R tyrosine kinase inhibitors are under development for clinical applications." (PMID 27846891, 2016). "In addition, antibody-mediated neutralization of peripheral macrophage CSF-1R was reported to block the development of sickness behavior measured by reduced locomotor activity and body weight loss in response to CD40 activation, a model of autoimmune disease." (PMID 32475344, 2020).
brain malformations (3 papers, 2021 to 2022). "Since the discovery of CSF1R mutations in 2012, conditions such as HDLS, ASLP, brain malformations, and skeletal dysplasia have been considered as part of the varied phenotypic spectrum of a unified disease." (PMID 35721475, 2022).
CADASIL (3 papers, 2017 to 2019). "Common genetic leukoencephalopathies discussed in detail include CSF1R, AARS2, cerebral arteriopathy with subcortical infarcts and leukoencephalopathy (CADASIL), and mitochondrial and metabolic disorders." (PMID 30467211, 2019).
chondrosarcoma (3 papers, 2020 to 2023). A malignant cartilaginous matrix-producing mesenchymal neoplasm arising from the bone and soft tissue. "Colony stimulating factor 1 receptor (CSF-1R) was expressed by tumor associated macrophages in 89.7% of dedifferentiated chondrosarcoma and 62.9% in conventional chondrosarcoma." (PMID 32707689, 2020). "On the other hand, CSF1R expression was observed in STSs with complex genomic profiles and chondrosarcoma." (PMID 37958467, 2023). "CSF1R+ macrophages were found in the peripheral areas of grade 2 and 3 chondrosarcomas and in the dedifferentiated compartment of dedifferentiated chondrosarcomas." (PMID 37958467, 2023). "In chondrosarcoma, the expression of CSF1R was involved in macrophage survival and proliferation and varied between conventional and dedifferentiated chondrosarcoma (64% of the conventional chondrosarcomas, and around 85% of the dedifferentiated chondrosarcomas were positive for CSF1R)." (PMID 37958467, 2023). "Similarly, SIRPA+ and CSF1R+ TAMs were related to the metastatic status at diagnosis and a poor OS in patients with dedifferentiated chondrosarcoma." (PMID 37958467, 2023). "In this study, increased expressions of lymphocyte activation gene-3 (LAG3), T cell immunoglobulin mucin (TIM3), B7 superfamily member-H3 (B7H3), signal regulatory protein alpha (SIRPA), and colony-stimulating factor 1 receptor (CSF1R) were observed in chondrosarcoma." (PMID 35163019, 2022).
chronic myeloid leukemia (3 papers, 2011 to 2019). "IM is a tyrosine kinase inhibitor in use for the clinical management of chronic myeloid leukemia and has been shown to inhibit several different kinases, including CSF-1R." (PMID 22096574, 2011).
colon adenocarcinoma (3 papers, 2020 to 2022). "We generated mice with CSF1R-deficient macrophages and induced lung and colon adenocarcinoma–associated MPE." (PMID 35315360, 2022). "The expression of CSF-1R in colon adenocarcinoma (COAD) and its prognostic value remain incompletely understood." (PMID 35444953, 2022). "We also examined the therapeutic potential of a clinically relevant CSF1R inhibitor (BLZ945) in lung and colon adenocarcinoma–induced experimental MPE." (PMID 35315360, 2022).
diabetic retinopathy (3 papers, 2011 to 2025). "In response to the injection of glycated albumin, a protein associated with diabetic retinopathy, cultured rat retinal microglia upregulate CSF-1 secretion and increase CSF-1 receptor (CSF1R) expression." (PMID 39683685, 2024). "Moreover, the high-affinity binding of M-CSF to CSF-1R plays a role in mononuclear/macrophage-associated diabetic complications, including diabetic retinopathy." (PMID 21266043, 2011). "Our results indicate that M-CSF acts as a costimulatory molecule to synergize GA-induced microglial inflammation via binding to its overexpressed receptor CSF-1R in diabetic retinopathy." (PMID 21266043, 2011). "Our present study demonstrate that M-CSF/CSF-1R signaling represents a further link between microglial inflammation and diabetic retinopathy and raises the possibility of specific therapies for targeting microglia-mediated injury in diabetic retinopathy." (PMID 21266043, 2011). "The increased microglial expression of M-CSF/CSF-1R not only is a response to microglial activation in diabetic retinopathy but also augments the microglial inflammation responsible for the diabetic microenvironment." (PMID 21266043, 2011). "Given the small amount of information available concerning CSF-1R expression by microglia in the diabetic environment, the regulatory role of M-CSF/CSF-1R signaling in microglial inflammation in diabetic retinopathy is unknown." (PMID 21266043, 2011).
diffuse large B-cell lymphoma (3 papers, 2015 to 2022). "The protein expression of CSF1R was analyzed by immunohistochemistry in 198 cases of diffuse large B-cell lymphoma, and it was found that high CSF1R-positive TAMs were associated with poor progression-free survival." (PMID 36358737, 2022).
endometrial cancer (3 papers, 2016 to 2024). Primary or metastatic malignant neoplasm involving the endometrium (mucous membrane that lines the endometrial cavity). "In addition, blocking CSF-1 receptor (CSF-1R) can prevent macrophage infiltration and endometrial cancer cell proliferation." (PMID 34717710, 2021). "CSF1/CSF1R inhibitors such as MCS110, Pexidartinib (PLX3397, PLX108-01) and Emactuzumab (RG7155) are being studied in clinical trials in solid tumors including ovarian and endometrial cancers." (PMID 34717710, 2021).